ADCY9 (adenylate cyclase 9)
Diseases named in the same sentence as ADCY9 in open-access papers:
ADCY9 is named in the same sentence as 59 diseases in open-access papers, as found by Europe PMC text mining. Sharing a sentence is not in itself a finding about the gene and the disease. The quoted sentences say what the papers report.
asthma (7 papers, 2017 to 2025). "In this study, we evaluated the profile of the known polymorphisms within the ADRB2 and ADCY9 genes of pharmacogenetic interest for the treatment of asthma." (PMID 39057056, 2024). "Using follow-up bioinformatics analyses, we also confirmed that two novel genes (SETDB1 and ZNF8) and three previously reported genes (DOCK8, MMP20, and ADCY9) are potential asthma-associated genes." (PMID 37569643, 2023). "We identified two potentially novel (SETDB1 and ZNF8) and five previously reported (DM4C, DOCK8, MMP20, MYL7, and ADCY9) genes associated with increased asthma risk." (PMID 37569643, 2023). "A previous study evaluating the interaction between ADCY9 gene polymorphisms and asthma in Brazilian children, and another trial using genome-wide association studies in obesity, indicated that ADCY9 rs2531995 was responsible for ADCY9 expression and intracellular cAMP production." (PMID 34683946, 2021). "Chelidonium majus relieved OVA-induced asthma in rats by regulating the Alox15, P4ha1, Pla2g16, Pde3a, Nme1, Entpd8 and Adcy9 genes expression to restore the disorders in energy metabolism and inflammation." (PMID 38671520, 2024).
Obesity (7 papers, 2017 to 2025). Accumulation of substantial excess body fat. "In male offspring, associated dmCpGs were linked to known obesity-related genes including B4GALNT4 (cg25020933, cg15762098), ADCY9 (insulin secretion and thyroid hormone synthesis) (cg00610508), ADRB1 (cg13848598) and ATP10D (cg14009629)." (PMID 40410506, 2025). "The results revealed that 18 of the DMR genes were associated with addiction and obesity (ADCY3; ADCY9; ATF4; CDK5R1; CHRNB2; GABRD; GABRG3; GNB1; GNB3; GRK5; HDAC4; HDAC9; MAP2K1; PDE11A; PDE2A; PDE3A; PPP1CA; SLC6A3)." (PMID 34389046, 2021). "Based on the obtained results, the ZSCAN32, PLCD4, HOXC13, and ADCY9 from obesity predicted genes, as well as LIMA1, and SLC22A23 from CRC predicted genes were significantly related to CRC survival rate." (PMID 33073494, 2020).
breast carcinoma (6 papers, 2013 to 2021). "In addition, ADCY9 is a known target of microribonucleic acids-−142-3p, which is associated with the invasiveness of breast cancer cells." (PMID 32983975, 2020). "Some research found that ADCY9 acts as a key gene in the cisplatin response regulatory network in the pro-apoptotic stage in breast cancer treatment, and overexpression of ADCY9 is a poor prognostic marker for disease-free survival in colon cancer." (PMID 33024640, 2020). "The expression of ADCY9 was regulated by estradiol in the human MCF-7 breast cancer cell line." (PMID 33936178, 2021).
colon cancer (4 papers, 2020 to 2021). "A higher expression level of ADCY9 was found in colon cancer and was an indicator of a bad prognosis." (PMID 34595103, 2021). "The ADCY9 expression remarkably increased in colon tumor tissue and can be a poor prognostic factor for colon survival." (PMID 33073494, 2020).
malaria (4 papers, 2010 to 2020). Malaria is a serious and sometimes fatal disease caused by a parasite that commonly infects a certain type of mosquito which feeds on humans. "Previous studies have shown that ADCY9 gene polymorphisms were related to the development of many diseases, including cardiovascular diseases, mood disorders, malaria, asthma, and allergy." (PMID 32983975, 2020). "Previous studies also reported that the SNPs in ADCY9 were associated with stroke, malaria, medicine responses, and cancer." (PMID 32983975, 2020). "Nonetheless, ADCY9 rs2230739 may act to upregulate TGFβ transcription, with the heterozygotes providing some selective advantage since the raised TGF-β levels will down-regulate proinflammatory cytokines, such as TNF, and protect against severe malaria." (PMID 24934404, 2014).
depression (3 papers, 2021 to 2023). "The correlation of Adcy9, Apc, Camk2b, Camk2g, and Ctnnd2 with the pathological mechanisms of depression was first reported in the present work." (PMID 34520625, 2021). "Adcy9−/− also showed no exploratory differences in the open field test and displayed similar levels of anxiety and depression‐like behavior as demonstrated in the elevated plus maze and forced swim tests." (PMID 36254885, 2022).
Stroke (3 papers, 2020 to 2023). Sudden impairment of blood flow to a part of the brain due to occlusion or rupture of an artery to the brain. "Five single nucleotide polymorphisms (SNPs) tested in children with SCD were significantly associated with stroke risk, namely ANXA2 (rs11853426), TEK (rs489347), and TGFBR3 (rs284875) variants, whereas ADCY9 (rs2238432) and ∝ -thalassemia were linked with decreased stroke risk." (PMID 35781614, 2023). "SNP rs2238432 in the ADCY9 gene was linked with decreased stroke risk." (PMID 33936178, 2021).
Anxiety (2 papers, 2022 to 2025). Intense feelings of nervousness, tension, or panic often arise in response to interpersonal stresses. "Interestingly The opioid signaling pathway revealed a small group of genes associated with fear and anxiety (ADCY9, ITPR1) which could alter fear response and be responsible for the previously observed extinction deficits." (PMID 40560842, 2025).
Bradycardia (2 papers, 2017 to 2022). A slower than normal heart rate (in adults, slower than 60 beats per minute). "We previously reported a bradycardia in Adcy9−/− mice under anesthesia." (PMID 36254885, 2022).
cerebral malaria (2 papers, 2012 to 2014). A sequestration of Plasmodium falciparum in the brain, which can cause coma and/or seizures. "Adenylate cyclase (AC) type 9 gene (ADCY9) is an interesting candidate gene since it is critical in neuronal signalling and thus may be relevant in the pathogenesis of cerebral malaria." (PMID 24934404, 2014).
coronary artery disease (2 papers, 2019 to 2023). "Adcy9, which encodes an adenylyl cyclase, can regulate the metabolism associated with the estrogen receptor pathway and is a sex-specific gene in patients with coronary artery disease." (PMID 36834847, 2023).
endometrial cancer (2 papers, 2020). Primary or metastatic malignant neoplasm involving the endometrium (mucous membrane that lines the endometrial cavity). "GPI, GPT, and LPCAT1 were frequently overamplified in endometrial cancer patients, while ADCY9 more often had missense mutations (unknown significance)." (PMID 32894095, 2020). "ADCY9 expression was found to be significantly different in endometrial cancer when compared to the controls, which might be involved in the pathogenesis of this cancer." (PMID 32983975, 2020).
granulomatosis with polyangiitis (2 papers, 2020 to 2022). A small-vessel necrotizing vasculitis characterized by the association of inflammation of the vessel wall and peri- and extravascular granulomatosis. "For example, overexpression of miR‐142‐3p in patients with granulomatosis with polyangiitis reduced the expression of target gene adenylate cyclase 9 (ADCY9), which is an enzyme that catalyses the conversion of ATP into cAMP." (PMID 32881301, 2020).
hepatocellular carcinoma (2 papers, 2020 to 2023). A malignant tumor that arises from hepatocytes. "The association between ADCY9 gene polymorphisms and hepatocellular carcinoma risk in subgroup of gender." (PMID 32983975, 2020). "The association between ADCY9 gene polymorphisms and hepatocellular carcinoma risk in subgroup of age." (PMID 32983975, 2020). "The aim of this study was to investigate whether ADCY9 gene polymorphisms could contribute to the susceptibility of hepatocellular carcinoma (HCC) in the Chinese Han population." (PMID 32983975, 2020). "Associations between ADCY9 gene polymorphisms and hepatocellular carcinoma risk." (PMID 32983975, 2020). "The most interesting case for the expression control analysis was that of ADCY9, a biomarker for glioma, lung, and hepatocellular carcinoma, as well as colorectal, bladder, and pancreatic cancers." (PMID 38132440, 2023).
lung adenocarcinoma (2 papers, 2021 to 2024). A carcinoma that arises from the lung and is characterized by the presence of malignant glandular epithelial cells. "Similarly, ADCY9, downregulated by a somatic eQTL in non-coding PIF positioned 191,184 bp upstream, has been recently identified as a novel tumour suppressor in lung adenocarcinoma." (PMID 39367275, 2024). "Interestingly, α1 integrinI (ITGA1) mRNA and adenylyl cyclase 9 (ADCY9) mRNA competed for binding to miR-181b, and ZEB1 upregulated ITGA1 to activate a miR-181b-regulated ceRNA network that increased metastasis of lung adenocarcinomas." (PMID 33741027, 2021).
lung carcinoma (2 papers, 2021 to 2023). "The PRKCD and ADCY9 had lower expression in lung normal tissues compared with lung cancer tissues in LUAD." (PMID 33936178, 2021). "Under the stimulation of the internal and external environment, the ADCY9 expression may change with the occurrence and development of lung cancer." (PMID 33936178, 2021).
melanoma (2 papers, 2024 to 2025). A malignant, usually aggressive tumor composed of atypical, neoplastic melanocytes. "Supporting this, the adenyl cyclase gene, ADCY9, and the PKA catalytic subunit alpha (PRKACA) were identified as key resistance effectors in melanoma, with PRKACA displaying the highest rescue score among serine/threonine kinases in a gain-of-function resistance study." (PMID 40719625, 2025).
mood disorder (2 papers, 2014 to 2017). A cognitive disorder a disturbance in which the person's mood is hypothesized to be the main underlying feature. "However, Toyota and colleagues reported only a weak association of ADCY9 gene variation with mood disorders." (PMID 24934404, 2014).
pancreatic cancer (2 papers, 2020 to 2023). "Rs2230739 of ADCY9 was involved in various pathways and processes, which might contribute to the susceptibility of pancreatic cancer." (PMID 32983975, 2020).
Acidosis (1 paper, 2012). Abnormal acid accumulation or depletion of base. "Furthermore, heterozygosity for the rs2230739 SNP in the ADCY9 gene, encoding an adenylate cyclase, was associated with a 50% reduction in the risk of acidosis (AG vs. AA/GG, OR = 0.516, 95% CI 0.302–0.882, p = 0.0129)." (PMID 23144702, 2012).
African trypanosomiasis (1 paper, 2025). "KEGG pathway enrichment analysis of these shared genes (corrected p < 0.05) revealed significant overrepresentation in glutamatergic synapse (encompassing HOMER1, HOMER2, PLCB4, and ADCY9) and African trypanosomiasis (containing SELE, MYD88, and PLCB4)." (PMID 41153960, 2025).
alcohol addiction (1 paper, 2020). "The data presented here extend the previously reported association of ADCY9, PECAM1, and IL4 with nicotine or alcohol addiction and psychiatric disorders." (PMID 33328875, 2020).
anaemia (1 paper, 2014). "Nevertheless, a number of marginal protective genotype associations were also observed between specific gene mutations and anaemia (CFTR, GNAS), hyperparasitaemia (DERL3, GBP7), hyperpyrexia (GBP7, ABO) and SMA (HbS, ADCY9)." (PMID 24934404, 2014).
celiac disease (1 paper, 2015). An autoimmune genetic disorder with an unknown pattern of inheritance that primarily affects the digestive tract. "Seven genes were down-regulated in the biopsies of celiac disease patients, among them NTS down-regulated 3.6 fold and the INSR, APPL2, ADCY9, GLS, HSPB1 and KIF13A 1.5-2.2 fold in the patient group (p < 0.001)." (PMID 26123480, 2015).
gastric cancer (1 paper, 2013). A primary or metastatic malignant neoplasm involving the stomach. "Different levels of ADCY7 and ADCY9 were detected in gastric cancer and normal cell lines." (PMID 24113161, 2013).
heroin addiction (1 paper, 2020). "Our study provides evidence for the association of ADCY9, PECAM1, and IL4 with heroin addiction through stringent bioinformatics analysis." (PMID 33328875, 2020).
intracranial aneurysms (1 paper, 2021). "The expression of ADCY9 was downregulated in intracranial aneurysms." (PMID 33936178, 2021).
leukemia (1 paper, 2021). A malignant (clonal) hematologic disorder, involving hematopoietic stem cells and characterized by the presence of primitive or atypical myeloid or lymphoid cells in the bone marrow and the blood. "Among the metabolic genes downregulated in NPM1/cohesin-mut compared with NPM1-mut AML, CHST13, ADCY9, PRR16, LPL, and SLC1A3 were confirmed by STAG2-deficient model of NPM1-mut leukemia." (PMID 34193978, 2021).
muscular atrophy (1 paper, 2025). The loss of muscle tissue due to inactivity or disease. "Within this pathway, HOMER1 regulates myofiber differentiation, HOMER2 associates with microgravity-induced muscular atrophy, and ADCY9-mediated cAMP signaling maintains muscle mass and function." (PMID 41153960, 2025).
Respiratory distress syndrome (1 paper, 2021). "Respiratory distress syndrome was associated with fetal single nucleotide polymorphisms in ADCY9." (PMID 33936178, 2021).
Sinus bradycardia (1 paper, 2021). Bradycardia related to a mean resting sinus rate of less than 50 beats per minute. "AC9 is essential for cardiac pacemaking as null mutants for Adcy9 present sinus bradycardia and a diastolic dysfunction with preserved ejection fraction." (PMID 34940515, 2021).
viral infection (1 paper, 2025). "Overexpression of JAK1, TYK2, MAP2K1, IFNG, TRPM2, and ADCY9 significantly inhibited viral infection, whereas overexpression of SNX27, GATA4, EHMT2, PCBP2, SMARCA4, and SLX4 enhanced viral infection." (PMID 40530850, 2025).
cancer (12 papers, 2014 to 2025). A tumor composed of atypical neoplastic, often pleomorphic cells that invade other tissues. "It has been reported that ADCY9 gene polymorphisms were associated with cancer development." (PMID 32983975, 2020). "The low ADCY9 level in cancer tissues is attributed to longer disease-free survival (DFS), while high ADCY9 expression and distant metastasis indicate a poor prognosis after treatment." (PMID 35832555, 2022). "The 3 most frequent DSV genes observed in cancer patients were identified as ADCY9, AURKAPS1, and RAB3GAP2 (p < 0.05)." (PMID 33431054, 2021). "In addition, studies have demonstrated that ADCY9 takes to participate in the regulation of cellular function in certain cancers and drug responses." (PMID 35627270, 2022). "Our study firstly demonstrated that ADCY9 gene polymorphisms were associated with HCC risk, especially rs2230742 significantly altered the susceptibility of HCC, and it confirmed that ADCY9 was involved in cancer development in previous studies." (PMID 32983975, 2020). "The potential function of ADCY9 in cancer development was also reported." (PMID 32983975, 2020). "The results showed that the downregulation of ADCY9 and NMUR1 in LUAD can inhibit the growth and aggressiveness of cancer, while the upregulation of SYT1 had the contrary effects." (PMID 35627270, 2022). "In this study, FKBP4, ADCY9, and KRAS were differentially expressed in cancer tissues and adjacent normal tissues of LUAD and were related to the prognosis of LUAD." (PMID 33936178, 2021). "In the CHRNB4-high subgroup, CHRNB4 was co-expressed with numerous genes, such as ADCY9, NOTCH3, ARNT, NCOA1, and NCOA3, which correlated with multiple cancer-related processes, but only one gene, FLT4, was co-expressed in the CHRNB4-low subgroup." (PMID 32455963, 2020).
tumor (9 papers, 2017 to 2024). "GEO datasets validated that the 6 genes (SHC1, FKBP4, NRAS, PRKCD, KRAS, ADCY9) had different expression between tumor tissues and adjacent normal tissues in LUAD, and 3 genes (FKBP4, KRAS, ADCY9) were related to the prognosis of LUAD." (PMID 33936178, 2021). "A screen performed to identify competing endogenous RNAs (ceRNAs) that govern metastasis revealed that the targets of the tumor suppressor miR-181b are integrin α1 (ITGA1) and adenylyl cyclase 9 (ADCY9)." (PMID 30463358, 2018). "Among them, SHC1, FKBP4, NRAS, KRAS had higher expression, and PRKCD, ADCY9 had lower expression in LUAD tumor tissues compared with normal tissue." (PMID 33936178, 2021). "Thus, we speculated that the high expression of ADCY9 and NMUR1 might facilitate the anti-tumor immunity in the LUAD microenvironment." (PMID 35627270, 2022).
heart disease (2 papers, 2020 to 2025). "Based on the literature and the genetic tests of the current patient, we speculate that the deletion of ADCY9 gene may be associated with severe heart disease in patients." (PMID 32321550, 2020).
cardiovascular disease (1 paper, 2021). "The interaction effect between the ADCY9 and CETP SNPs on both respiratory and cardiovascular phenotypes differs between the sexes, with effects on respiratory phenotypes limited to females and cardiovascular disease phenotype associations showing significant three-way sex-by-SNPs effects." (PMID 34609279, 2021).
respiratory diseases (1 paper, 2021). "Some studies found that ADCY9 is associated with respiratory diseases." (PMID 33936178, 2021).
ADCY9 also shares sentences with these, for which no sentence is quoted: atherosclerosis (3 papers); psychiatric disorder (3); diabetes (2); long QT syndrome (2); Alzheimer disease (1); Arrhythmia (1); Brugada syndrome (1); cardiac hypertrophy (1); colorectal cancer (1); glioma (1); heart failure (1); Hypercholesterolemia (1); hypertrophic cardiomyopathy (1); hypertrophy (1); multiple sclerosis (1); muscular dystrophy (1); myocardial infarction (1); ovarian carcinoma (1); Rubinstein-Taybi syndrome (1); Sjogren syndrome (1); Type 2 diabetes (1); uveitis (1).